DCTN4 (dynactin subunit 4)
Description:
Part of the dynactin complex that activates the molecular motor dynein for ultra-processive transport along microtubules.
Synonyms: Dyn4; p62
Tractability: PROTAC: UniProt records ubiquitination sites on it; ubiquitination databases record sites on it; its protein half-life has been measured.
Gene: Protein-coding gene on chromosome 5 (150,706,840 to 150,759,095, reverse strand). Ensembl gene ENSG00000132912.
Subcellular location: Cytoplasm, cytoskeleton; Cytoplasm, cytoskeleton, microtubule organizing center, centrosome; Cytoplasm, cytoskeleton, stress fiber; Cytoplasm, cell cortex; Cytoplasm, myofibril, sarcomere
Subcellular location (Human Protein Atlas): Centrosome; Nucleoplasm; Calyx
Pathways (Reactome):
Vesicle-mediated transport: COPI-independent Golgi-to-ER retrograde traffic; COPI-mediated anterograde transport
Cellular responses to stimuli: HSP90 chaperone cycle for steroid hormone receptors (SHR) in the presence of ligand
Immune System: MHC class II antigen presentation
Gene Ontology:
Molecular function: protein binding
Cellular component: centrosome; cytoplasm; cytosol; dynactin complex; nucleus; cell cortex; cytoplasmic dynein complex; cytoskeleton; focal adhesion; kinetochore; sarcomere; spindle pole; stress fiber
Genetic constraint (gnomAD): Loss-of-function variants: 15 observed, 42.09 expected, observed/expected ratio (o/e) 0.36, 90% interval 0.24 to 0.55. The upper end of that interval is the gene's LOEUF score, 0.55, which puts it in group 2 of 6, group 1 being the genes least tolerant of losing a copy. Missense variants: 391 observed, 466.07 expected, observed/expected ratio (o/e) 0.84, 90% interval 0.77 to 0.91. Synonymous variants: 157 observed, 168.78 expected, observed/expected ratio (o/e) 0.93, 90% interval 0.82 to 1.06.
Homologues: Orthologues: chimpanzee DCTN4 (99% identical), macaque DCTN4 (99% identical), guinea pig DCTN4 (99% identical), dog DCTN4 (99% identical), rabbit DCTN4 (97% identical), mouse Dctn4 (97% identical), rat Dctn4 (97% identical), pig DCTN4 (88% identical), tropical clawed frog dctn4 (86% identical), zebrafish dctn4 (85% identical), Drosophila melanogaster DCTN4-p62 (40% identical), Caenorhabditis elegans dnc-4 (27% identical).
Diseases named in the same sentence as DCTN4 in open-access papers:
DCTN4 is named in the same sentence as 26 diseases in open-access papers, as found by Europe PMC text mining. Sharing a sentence is not in itself a finding about the gene and the disease. The quoted sentences say what the papers report.
colon adenocarcinoma (4 papers, 2019 to 2022). "Previously, DCTN4 was reported to be associated with poor prognosis of colon adenocarcinoma and low-grade glioma." (PMID 35035484, 2022). "A previous study has revealed that DCTN4 was upregulated in colon adenocarcinoma and high expression was associated with prolonged overall survival." (PMID 35281472, 2022). "DCTN1, DCTN2, and DCTN4 could serve as biomarkers to predict the prognosis and diagnosis of colon adenocarcinoma (COAD)." (PMID 31847905, 2019).
cystic fibrosis (2 papers, 2015 to 2016). Autosomal recessive disorder caused by pathogenic variants in the CFTR gene (cystic fibrosis transmembrane conductance regulator), which encodes a chloride and bicarbonate channel expressed in epithelial cells, and follow the diagnosis criteria. "Exome sequencing of extreme phenotypes previously has identified DCTN4 as a modifier of chronic Pseudomonas aeruginosa infection in patients with cystic fibrosis." (PMID 27193124, 2016).
Huntington disease (2 papers, 2016 to 2023). Huntington disease (HD) is a rare neurodegenerative disorder of the central nervous system characterized by unwanted choreatic movements, behavioral and psychiatric disturbances and dementia. "We found genes that are related to cancer (NBN, FAM84B), Huntington's disease (DCTN4), Parkinson's disease (NUCKS1), Alzheimer's disease (SMC3), amongst others." (PMID 27257970, 2016).
lung disease (1 paper, 2024). "DCTN4 was also investigated as a GM that may affect lung disease progression and survival." (PMID 40225935, 2024).
lung fibrosis (1 paper, 2023). "No relevant data were found connecting dynactin subunit 4, RNA-binding protein 42, or 28S ribosomal protein S15 with macrophage function or lung fibrosis." (PMID 37024614, 2023).
pneumococcal meningitis (1 paper, 2016). An acute purulent infection of the meninges and subarachnoid space caused by Streptococcus pneumoniae, most prevalent in children and adults over the age of 60. "In the first genome wide association study on outcome in pneumococcal meningitis gene variants in AKT3, DCTN4 and RAET1E were associated with unfavourable outcome in adults with pneumococcal meningitis." (PMID 27193124, 2016). "In conclusion, we identified gene variants in AKT3, DCTN4 and RAET1E to be associated with unfavourable outcome in adults with pneumococcal meningitis." (PMID 27193124, 2016). "Genetic variants in DCTN4 and RAET1E were also associated with functional outcome in pneumococcal meningitis, but these findings will need to be validated." (PMID 27193124, 2016). "To explore the role of AKT3, DCTN4, and RAET1E during pneumococcal meningitis we determined their brain expression levels in our mouse model." (PMID 27193124, 2016).
tumor (3 papers, 2022). "The Wilcoxon rank-sum test showed that ALG8 (P < 0.001) had a higher expression level in tumor tissues compared with normal tissues, while DCTN4 (P < 0.001), DCTN6 (P < 0.001), and UBB (P < 0.001) had lower expression levels in tumor tissues." (PMID 35281472, 2022). "The expression of COPB2, DCTN4, RYK, TARS, and UIMC1 indicated association with the change of fraction of immune cells in LSCC patients; two genes, COPB2 and RYK, indicated different expression in various tumor stages of LSCC." (PMID 35715770, 2022). "Conversely, DCTN4 and DCTN6 were both observed to be downregulated in tumor tissues of OC compared with adjacent tissues in this study." (PMID 35281472, 2022). "We identified 14 prognostic DNA repair-related genes and provided evidence that DCTN4 and TAF13 may serve as a tumor promotor in TC." (PMID 35035484, 2022).
neurodegenerative disease (1 paper, 2025). A disorder of the central nervous system characterized by gradual and progressive loss of neural tissue and neurologic function. "Our contrasting findings raise new questions about the role of DCTN4 in AD and highlight the complexity of copper homeostasis in neurodegenerative diseases." (PMID 40149738, 2025).
DCTN4 also shares sentences with these, for which no sentence is quoted: cancer (2 papers); glioma (2); ovarian carcinoma (2); alcoholism (1); Alzheimer disease (1); bladder cancer (1); breast carcinoma (1); colon cancer (1); colorectal cancer (1); depression (1); gastric adenocarcinoma (1); gastric cancer (1); infection (1); non-small cell lung carcinoma (1); Parkinson disease (1); psychiatric disorder (1); skin cancer (1); testicular cancer (1).